LUM (lumican)
Diseases named in the same sentence as LUM in open-access papers (continued):
Sharing a sentence is not in itself a finding about the gene and the disease.
skin cutaneous melanoma (1 paper, 2017). "We found that LUM expression levels significantly correlate with a lower risk of poor prognosis for skin cutaneous melanoma patients, and therefore confirmed that overall survival is longer in cases exhibiting higher LUM expression." (PMID 28794454, 2017).
soft tissue sarcoma (1 paper, 2023). A malignant neoplasm arising from muscle tissue, adipose tissue, blood vessels, fibrous tissue, or other supportive tissues excluding the bones. "This approach was evaluated in a canine clinical trial that showed reprogramming of the TME in canine soft tissue sarcomas by IL-2 and IL-12 linked to lumican." (PMID 38063196, 2023).
steatosis (1 paper, 2016). Increased lipid within the cytoplasm of cells. "The expression of lumican was similarly abundant in obese patients with normal liver histology and in obese patients with simple steatosis; however, it was over-expressed in mild progressive NASH patients." (PMID 26999105, 2016).
stomach adenocarcinoma (1 paper, 2023). "Collectively, a thorough bioinformatics analysis was carried out and an AC117386.2/hsa-miR-378c/LUM regulatory axis in the stomach adenocarcinoma dataset was detected." (PMID 38129820, 2023).
stromal corneal dystrophies (1 paper, 2023). "The corneal stroma, on the other hand, was found to be composed of classic keratocyte markers, keratocan (KERA), lumican (LUM), and decorin (DCN), all of which are associated with stromal corneal dystrophies." (PMID 37138096, 2023).
tendinopathy (1 paper, 2017). "Increased LUM expression has been reported in stress deprived areas in other tendinopathy studies." (PMID 29023489, 2017).
type 1 diabetes (1 paper, 2020). "Singh and colleagues also reported that youths with type 1 diabetes excreted higher amounts of lumican, CD14, and various lysosomal proteins such as ASAH1, CTSD, and NAGA compared to their non-diabetic siblings." (PMID 32453760, 2020). "Increased urinary excretion of CD14 (P = 0.0057), HEXA (P < 0.0001), and lumican (P = 0.0014) was replicated in a second cohort of youths with and without type 1 diabetes." (PMID 32453760, 2020).
type II diabetes (1 paper, 2024). "LUM modulates adipocyte functional properties and aids in glucose homeostasis in obesity and insulin resistance associated with type II diabetes." (PMID 38474072, 2024). "LUM acts in an extracellular signal regulated kinase (ERK)-dependent manner and is a potential therapeutic target for adipose tissue-targeted therapeutics in type 2 diabetes." (PMID 38474072, 2024).
urothelial carcinoma (1 paper, 2024). A malignant neoplasm derived from the transitional epithelium of the urinary tract (urinary bladder, ureter, urethra, or renal pelvis). "Based on the expression of SDC1, LUM, VEGFA, TIMP3 and WNT7B in various urothelial carcinoma cell lines in the CCL database, we selected J82 and UMUC3 as the verification cell lines, and marked them with puromycin resistance labelling." (PMID 38183115, 2024).
Varicose veins (1 paper, 2023). Enlarged and tortuous veins. "We identified eight plasma proteins that are significantly associated with the risk of varicose veins after Bonferroni correction (P < 2.495 × 10−5), with five being protective (LUM, POSTN, RPN1, RSPO3, and VAT1) and three harmful (COLEC11, IRF3, and SARS2)." (PMID 37404740, 2023). "The COLEC11, IRF3, LUM, POSTN, RSPO3, and SARS2 were considered to share the same variant of varicose veins." (PMID 37404740, 2023). "The colocalization analysis indicated that COLEC11, IRF3, LUM, POSTN, RSPO3, and SARS2 shared the same causal variant with varicose veins." (PMID 37404740, 2023). "As a result, eight proteins were found to be causally associated with varicose veins, including COLEC11, IRF3, LUM, POSTN, RPN1, RSPO3, SARS2, and VAT1." (PMID 37404740, 2023). "Five of eight proteins in primary analysis were finally identified as potential drug targets for varicose veins, including IRF3, LUM, POSTN, RSPO3, and SARS2." (PMID 37404740, 2023). "A comprehensive analysis indicated that IRF3, LUM, POSTN, RSPO3, and SARS2 might be potential drug targets for varicose veins." (PMID 37404740, 2023).
tumor (168 papers, 2007 to 2025). "This research is the first attempt to comprehensively analyze the link between LUM expression, the infiltration of tumor-associated immune cells, and the ceRNA network in STAD." (PMID 38129820, 2023). "In another trial with colorectal adenocarcinoma, lumican is shown to have close correlations with the infiltration levels of immune cells including the tumor-associated macrophages, regulatory T cells, and dendritic cells." (PMID 37504302, 2023). "On the contrary, LUM expressions have been suggested to attenuate tumor progression, which is associated with favorable clinical outcomes." (PMID 37692065, 2023). "The available knowledge on the role of lumican in the processes of tumor-associated inflammation is restricted." (PMID 34572532, 2021). "Vimentin and lumican have long been known as cancer-associated proteins and are involved in tumor growth and metastasis." (PMID 30440021, 2018). "Yet, it has to be noticed that the baseline level of tumor-infiltrating T lymphocytes surprisingly shows a marked 75% decrease under lumican deficiency." (PMID 28794454, 2017). "None of the 8q, 13q, or 20q chromosomal aberrations was associated with lumican staining in the epithelial cells or tumor stroma." (PMID 28481899, 2017). "Further studies should address the diagnostic value of lumican and investigate its role in tumor progression." (PMID 25961303, 2015). "Any possible association of lumican IHC expression with tumor grade, stage (pTNM), and vascular/pleural invasion (evaluated on hematoxylin & eosin stained slides) was ruled out in resected AdCs." (PMID 25961303, 2015). "Others have previously shown that matrix proteoglycans lumican and decorin are abundant components of breast tissue stroma and that altered expression of lumican and decorin is associated with tumor progression and outcome." (PMID 21791066, 2011). "High levels of LUM in cancer tissue may lead to chemoresistance, increasing malignancy risk and potentially promoting tumor growth." (PMID 40789825, 2025). "Younger age, higher tumor grade, lower ER level are associated with higher lumican expression." (PMID 40927672, 2025). "Cumulatively, our results revealed that the overexpression of LUM might associate with tumor progression." (PMID 38129820, 2023). "It has been reported that LUM affects inflammatory as well as immune responses and may be a potential tumor-associated inflammatory modulator." (PMID 37692065, 2023). "LUM encodes the lumican proteoglycan, a major component of the extracellular matrix, and plays an important role in angiogenesis, regulation of collagen fibrogenesis, cell invasion, and growth, which are important activities in tumor progression." (PMID 36982287, 2023). "In addition, several molecules associated with tumor mechanisms and related to tumor immune responses such as gelsolin, periostin, osteopontin, lumican and vitamin D, were identified in the PC secretome dependent on GB-induced CMA." (PMID 35419364, 2022). "At last, larger tumor size, T1 disease, BoM, and LiM were independently associated with LuM." (PMID 36733675, 2022). "Moreover, LinkedOmics demonstrated that the LUM expression was strongly associated with miR200 family expression and tumor immune escape." (PMID 34572532, 2021). "Despite the lack of studies revealing a direct relevance between LUM and IFNG response, lumican plays a role in extracellular matrix remodeling, tumor-associated inflammatory response, and GBM resistance to TMZ, and perhaps is involved in the evasion of IFNG killing by GBM." (PMID 34566988, 2021). "Moreover, the downregulation of lumican was implicated in maCM-mediated invasion with a potential role in tumor-associated inflammatory response.The potential role of lumican in response to inflammation is needed to be investigated." (PMID 29549325, 2018).
tumor (continued). "Indeed, a striking linearization of interstitial collagens is observed within tumors recovered from lumican-deficient mice as compared to WT, with those typical morphological changes being correlated to a promotion of tumor growth." (PMID 28794454, 2017). "Interestingly, we also noticed a 75% decrease in basal levels of tumor-infiltrating T cells under lumican deficiency." (PMID 28794454, 2017). "Hence, we found that host lumican deficiency promotes a pro-angiogenic tumor phenotype through significant increase of both intratumoral functional vessels number and diameter." (PMID 28794454, 2017). "Next, we investigated whether lumican or versican expression was associated with one of the tumor-progression chromosome CNAs, i.e. gain of chromosome 8q, 13q, or 20q." (PMID 28481899, 2017). "So as to decipher whether host lumican deficiency may modulate tumor response to ECM-targeted therapeutic approach, we considered a previously validated anti-angiogenic peptide named TAX220, 22–24." (PMID 28794454, 2017). "Therefore, we postulate that the LUM protein is mostly produced by CAFs and may be one of the causes of disease deterioration in tumor patients." (PMID 37692065, 2023). "Moreover, in subgroup analysis, tumor size was significant associated with BoM, LiM, and LuM." (PMID 36733675, 2022). "Based on a quantitative comparison between tumor and NAT ECM, we observed a substantial loss of PROs (i.e., DCN, OGN, LUM, and HAPLN1)." (PMID 40032993, 2025). "While LUM shows promise as a PDAC biomarker due to its involvement in the tumor microenvironment and key signaling pathways, further research is needed to fully understand its diagnostic and prognostic value." (PMID 40789825, 2025). "In cancer biology, LUM expression in the tumor microenvironment can have either pro-tumorigenic or anti-tumorigenic effects." (PMID 40789825, 2025). "In contrast, stromal CAFs exhibit increased expression of ECM components, such as POSTN and LUM, promoting tumor cell invasion and metastasis through ECM hardening." (PMID 41408647, 2025). "LUM impedes tumor growth through its MMP inhibitory activity, affects focal adhesions and the migration and growth of tumor cells through interaction with α2β1 integrin and inhibitory effects on angiogenesis." (PMID 40141196, 2025). "Regarding the proteoglycan metabolism, this study found significant decreased levels of UDP-GlcDH in tumor samples, as well as of lumican, decorin, and mimecan." (PMID 39195201, 2024). "LUM+ tumor cells were mainly enriched in proteoglycans in cancer and extracellular matrix organization and demonstrated expression of the MMP2, MMP14, COL1A1, COL6A2, and COL1A2 genes, associated with extracellular matrix remodeling." (PMID 39685635, 2024). "The secretion of extracellular matrix (ECM) proteins with anti-tumor (Lumican) and pro-tumoral (Osteopontin, OPN) properties was shown to be dependent on the regulation of GB-induced CMA in PCs." (PMID 39796053, 2024). "LUM+ tumor cells demonstrated a high expression of LUM, GPNMB, and CAVIN1 genes linked to low sensitivity to doxorubicin." (PMID 39685635, 2024). "It is well established that lumican controls tumor cell proliferation in a cancer type-dependent manner." (PMID 39334952, 2024). "The LUM gene, encoding a member of the small leucine-rich proteoglycan (SLRP) family, is known to regulate ECM organization and is involved in tumor development and progression." (PMID 39766023, 2024). "As expected, brain areas with GB tumor mass only showed Lumican expression within the tumor cell mass and in the peritumoral GB cell infiltration." (PMID 39796053, 2024). "In contrast, Lumican secretion was found to be enriched in the secretome of CMA-deficient PCs responding to GB cells, among other molecules contributing to the anti-tumor immune responses." (PMID 39796053, 2024).
tumor (continued). "Cancer-associated fibroblasts in gastric cancer express lumican, which promotes the activation of the integrin β1–FAK signaling pathway, resulting in increased cancer cell proliferation and tumor progression." (PMID 39334952, 2024). "In the cell–matrix interaction, decorin and lumican represent small leucine-rich proteoglycans and critical matrix constituents reported to modulate the functions of tyrosine kinase receptors in tumor cells, including IGF1R and IR-A." (PMID 38892104, 2024). "In contrast, Lumican was significantly identified in perivascular areas surrounding brain parenchyma where there was a previous tumor mass and infiltrated GB elimination." (PMID 39796053, 2024). "Previous studies have substantiated that LUM is involved in tumor cell biology via modulating tumor inflammatory signal transduction." (PMID 38129820, 2023). "The LUM protein expression was predominantly located in the cytoplasm of tumor cells, as observed through immunoreactivity." (PMID 38129820, 2023). "LUM not only regulates extracellular water balance and collagen fiber formation but also impacts tumor growth, adhesion and migration." (PMID 37519786, 2023). "Recently, increasing experimental data have shown that LUM is expressed in various types of tumor tissues." (PMID 37519786, 2023). "GC tissues showed levels of LUM expression that differed from those of non-cancerous adjacent tissues, with 84.8% (39/46) of tumor specimens displayed LUM protein expression but exhibited a wide range of variation, from weak to very strong expression." (PMID 38129820, 2023). "Based on these results and findings, it can be concluded that LUM affects the infiltration of the immune cells in the tumor microenvironment and contributes to poor prognosis in GC patients." (PMID 38129820, 2023). "Recently, lumican was reported to be fused to therapeutic cytokines for cancer immunotherapy, which prolonged the retention of drugs in tumor and reduced side effects." (PMID 37692860, 2023). "Proteoglycans in cancer is the most enriched pathway associated with MEIS1 and HOXB13 inhibition, inducing tumor suppression and DCN, LUM, and TGFBR3, as well as regulating growth factor, migration, and invasion signaling through receptor tyrosine kinases." (PMID 36661515, 2023). "Lumican is a class II small leucine-rich proteoglycan that regulates cancer proliferation within the tumor microenvironment." (PMID 37363395, 2023). "In conclusion, we found that PAAD was the only tumor in our study with consistently elevated LUM expression in all three analyses: RNA analysis, protein analysis, and immunohistochemical analysis." (PMID 37692065, 2023). "Simultaneously, LUM regulates the proliferation, migration, and tube formation of primordial epithelial cells, contributing to tumor angiogenesis." (PMID 38129820, 2023). "Among them, SKCM was the tumor with the highest LUM mutation frequency, with 6.08%, while 3.53% of SARC patients had LUM gene amplification." (PMID 37692065, 2023). "In this study, we aimed to explore the links among LUM expression, survival, tumor microenvironment (TME), and immunotherapy in 33 cancer types." (PMID 37692065, 2023). "Despite the fact that LUM expression values decreased in some tumor stages, from an overall point of view, the expression of LUM showed an increasing trend with the tumor stage." (PMID 37692065, 2023). "After integrating the GTEx and TCGA databases, we compared differences in expressions of LUM between normal and tumor samples." (PMID 37692065, 2023). "Most of these genes were tumor cell metastasis-associated genes such as TNC, PLAU, PDPN, SPARC, LUM, and especially SNAI2 (Zinc finger protein SLUG transcription factor)." (PMID 35742914, 2022). "According to univariate analyses, age, race, tumor site, histology, tumor grade, tumor size, BoM, BrM, LuM, and chemotherapy were related to OS and CSS." (PMID 36168908, 2022).
tumor (continued). "A multivariate Cox regression model further revealed that age, histology, tumor grade, BoM, BrM, LuM, and chemotherapy remained statistically significant as predictors for OS and CSS." (PMID 36168908, 2022). "This subset expressed many of the ECM components identified by mass spectrometry of tumor material: collagen VI, fibronectin, lumican, laminin and collagen XII." (PMID 36077607, 2022). "According to univariate and multivariate analyses, several variables were determined as independent risk factors for LiM, including gender, age, tumor site, histology, tumor grade, tumor size, T stage, regional lymph node, BoM, BrM and LuM." (PMID 36168908, 2022). "The overall results suggested that Lumican is usually overexpressed in tumor tissue or cancer cells." (PMID 36361971, 2022). "Some studies have shown that LUM is involved in tumor inflammatory signal transduction, which affects the development of tumors by binding to integrin subunits such as β2, α, and αL on polymorphonuclear leukocytes." (PMID 35433865, 2022). "Both LUM and CSPG encode proteoglycans, and pericytes are being increasingly recognized as key players in tumor vessel formation and growth." (PMID 34642171, 2022). "Proteoglycans such as HSPG2 (perlecan), lumican and biglycan were identified in tumor ECM, although their abundance was similar to that in healthy cortex." (PMID 36077607, 2022). "Recently, LUM has been reported to regulate cell behavior during embryonic development, tissue repair and tumor progression." (PMID 34461940, 2021). "Many studies have shown that lumican modulates tumor cells’ proliferation, invasion, and metastasis with different mechanisms, either enhancing or preventing cancer progression." (PMID 34572532, 2021). "Some components repelled certain cell types, for example, TGFBI, which decreased cell attachment of fibroblasts, and lumican and tenascin C, which reduced attachment of tumor cells." (PMID 34884982, 2021). "Based on subgroup analysis using clinicopathological features (tumor grade and cancer stage), we found that VCAN, EFNA4, and LUM have significantly higher expressions in patients with tumor grade than in healthy individuals." (PMID 34093807, 2021). "The expression level of lumican in cancer cells of lung adenocarcinomas was positively correlated with pleural invasion and larger tumor size." (PMID 34638415, 2021). "Lumican is known to modulate collagen fibrillogenesis and integrin signaling and has been shown to have a tumor-suppressive effect in several cancers." (PMID 32887625, 2020). "At the same time, lumican regulates tumor angiogenesis by participating in the formation of the tubular structure of epithelial primordial cells, which in turn affects tumor proliferation." (PMID 32500021, 2020). "The chi-square test showed that the high expression of LUM was correlated with tumor differentiation (P = 0.024) and T stage (P = 0.004)." (PMID 32500021, 2020). "Cell adhesion to the ECM and the development of bone metastasis was decreased after downregulation of lumican expression, suggesting that lumican promotes bone metastasis by modulating the interaction between tumor cells and the ECM." (PMID 31963522, 2020). "The expression of LUM increased with poor differentiation and was upregulated with increasing tumor stage." (PMID 32500021, 2020). "To directly examine the role of lumican in tumor metastasis, we transfected a lumican-specific short hairpin RNA (shRNA) vector into the bone metastatic LLC/luc BM 2nd cells." (PMID 31963522, 2020). "Although the effects of lumican overexpression in different cancers were contradictory, the involvement of lumican in the regulation of tumor growth, cell mobility, and ECM attachment was demonstrated clearly." (PMID 31963522, 2020). "On this basis, a further analysis of the relationship between LUM expression and clinicopathological parameters showed that the high expression level of LUM was significantly correlated with tumor differentiation and T stage." (PMID 32500021, 2020).